RGPD3 (RANBP2 like and GRIP domain containing 3)
Synonyms: RGP3
Tractability: PROTAC: ubiquitination databases record sites on it.
Gene: Protein-coding gene on chromosome 2 (106,391,290 to 106,468,413, reverse strand). Ensembl gene ENSG00000153165.
Subcellular location (Human Protein Atlas): Nuclear membrane; Vesicles
Gene Ontology:
Molecular function: SUMO transferase activity
Biological process: NLS-bearing protein import into nucleus; nuclear export
Cellular component: nuclear pore; Golgi apparatus
Genetic constraint (gnomAD): Loss-of-function variants: 57 observed, 91.63 expected, observed/expected ratio (o/e) 0.62, 90% interval 0.5 to 0.78. The synonymous counts are far from expectation, so gnomAD's model fits this gene poorly and the ratio says little. Missense variants: 884 observed, 1,118.2 expected, observed/expected ratio (o/e) 0.79, 90% interval 0.75 to 0.84. Synonymous variants: 292 observed, 388.68 expected, observed/expected ratio (o/e) 0.75, 90% interval 0.68 to 0.83.
Homologues: Orthologues: zebrafish ranbp3a (5% identical), Drosophila melanogaster RanBP3 (5% identical). Paralogues in human: RGPD4 (98% identical), RGPD8 (95% identical), RGPD5 (95% identical), RGPD6 (95% identical), RGPD1 (95% identical), RGPD2 (95% identical), RANBP2 (84% identical), RANBP3 (7% identical), RANBP3L (4% identical), RANBP1 (4% identical).
Diseases named in the same sentence as RGPD3 in open-access papers:
RGPD3 is named in the same sentence as 4 diseases in open-access papers, as found by Europe PMC text mining. Sharing a sentence is not in itself a finding about the gene and the disease. The quoted sentences say what the papers report.
thyroid cancer (2 papers, 2023 to 2025). "Deleteriousness scores calculated using CADD revealed several variants with very high scores, including those in RGPD3, LRP1B, and RET, emphasizing their critical roles in thyroid cancer progression and therapeutic potential." (PMID 40297138, 2025). "Interestingly, SNPs associated with thyroid cancer (THCA) in three THCA driver genes were found to be under positive selection in the East Asian population (CUX1 and RGPD3) and the European population (HERC2)." (PMID 37098512, 2023). "Moreover, SNPs associated with thyroid cancer in three thyroid cancer driver genes (CUX1, HERC2 and RGPD3) were under positive selection in East Asian and European populations, consistent with the high incidence of thyroid cancer in these populations." (PMID 37098512, 2023).
RGPD3 also shares sentences with these, for which no sentence is quoted: breast carcinoma (1 paper); Hepatic steatosis (1); psychiatric disorder (1).